CRP (C-reactive protein)
Diseases named in the same sentence as CRP in open-access papers (continued):
Sharing a sentence is not in itself a finding about the gene and the disease.
diabetes (continued). "Higher serum C-reactive protein levels (6.6 ± 12.3 mg/dL, p = 0.04) along with higher levels of pro-inflammatory cytokines IL-6 (1.59 ± 1.19, pg/mL, p = 0.01) and TNF-α (1.49 ± 0.55 pg/mL, p = 0.01) indicated greater systemic inflammation in participants with diabetes." (PMID 40533477, 2025). "Stratified analyses further highlighted significant associations between Hs-CRP and POD in specific subgroups, notably in patients aged ≥65 years, female patients, and those with or without hypertension, diabetes, or stroke history, and without chronic kidney disease (p < 0.05)." (PMID 39958614, 2025). "Moreover, they showed higher values of glycemic (FPG and HbA1c) and inflammatory (CRP, TNF-alpha, and ESR) markers, as well as a lower GFR, and higher prevalence of hypertension, diabetes mellitus, ischemic heart disease, heart failure, peripheral artery disease, and stroke." (PMID 41106480, 2025). "The sex, presence of diabetes mellitus (DM), hypertension (HTN), coronary artery disease (CAD), albumin, urea clearance index (Kt/V (D)), and high-sensitivity C-reactive protein (hs-CRP) levels were similar between the high and low groups for all metabolites." (PMID 41226502, 2025). "This meta-analysis evaluates the effects of probiotics on C-reactive protein (CRP), tumor necrosis factor-alpha (TNF-α), interleukin-6 (IL-6), malondialdehyde (MDA), total antioxidant capacity (TAC), glutathione (GSH), and nitric oxide (NO) in patients with diabetes." (PMID 40123937, 2025). "Exploratory analyses incorporating CRP and lipid measures argued against major confounding in controls and MCI, however, unrecorded variables such as body-mass index, metabolic syndrome, diabetes, or hypertension could have contributed to variability in peripheral CHI3L1 expression." (PMID 41425914, 2025). "Additionally,since our primary endpoints—sUA levels, hs-CRP reduction, and survivaltrends—are independent of short-term glycemic fluctuations, the lack ofstratification by diabetes treatment does not significantly affect the validityof our conclusions." (PMID 40300646, 2025). "Subgroup analysis demonstrated that the inverse association between total testosterone and the risk of all-cause death remained significant regardless of factors such as age, race, body mass index, diabetes, hypertension, C-reactive protein, creatinine, and sex hormone binding globulin." (PMID 39014506, 2024). "Additionally, diabetic patients with nephropathy showed significantly increased CRP levels compared to those with type 2 diabetes mellitus who did not have nephropathy." (PMID 39354365, 2024). "In addition, among patients without diabetes, there is an elevation in the average of D-dimer (1153 ng/mL), CRP (63 mg/L), ALT (46 IU/L), and LDH (342 IU/L)." (PMID 39995847, 2024). "Notably, interaction tests revealed that gender, BMI, diabetes, hypertension, CKD and smoking or alcohol consumption status did not significantly influence the association between CRP and kidney stones." (PMID 38281018, 2024). "The patients with poor 7-year functional outcome were older and had a larger proportion of severe strokes, diabetes, previous strokes, and sedentary lifestyle compared to the patients with favorable outcome, and they also displayed higher levels of s-IGFBP-1, HOMA-IR, and hs-CRP." (PMID 38732147, 2024). "SEP indicators (education and income), risk factors (i.e., body mass index (BMI), total cholesterol, diabetes mellitus, coronary artery calcification, current smoking, hypertension, diet, no exercise) and blood serum CRP (mg/dl) were assessed at study baseline." (PMID 39715856, 2024). "However, we found that while adiponectin levels were higher among those with a normal BMI and without diabetes, leptin and CRP levels were higher in individuals with overweight, obesity, with prediabetes and diabetes." (PMID 38585953, 2024).
diabetes (continued). "Fourth, although this study focused on adjusting for potential risk factors for CKD, other unmeasured or residual confounding factors, including high-sensitivity C-reactive protein levels, medication status for diabetes and hypertension, etc., were not adequately adjusted." (PMID 38846493, 2024). "Among others, elevated levels of salivary glucose and inflammatory cytokines correlate with diabetes progression, while vascular endothelial growth factor (VEGF) and salivary C-reactive protein might be applicable as indicators for periodontal disease and cardiovascular risk." (PMID 39795606, 2024). "Moreover, they discovered an inverse correlation between 25(OH)D and mortality regardless of age, sex, diabetes, platelet count, and levels of IL-6, CRP, lactate dehydrogenase (LDH), neutrophils, and lymphocytes." (PMID 37727794, 2023). "When adjusting for age, sex, hypertension, smoking, diabetes, IHD, change in CRP levels and SIRT1 level at baseline in a multivariable model, significantly higher SIRT1 levels could still be observed at 48 months in the active group compared with the placebo group, (p = 0.006)." (PMID 36979007, 2023). "However, the results from the ADVANCE Study showed that IL-6 levels, a circulating inflammatory marker, rather than CRP or fibrinogen levels, were an independent predictor of macrovascular events and mortality in patients with diabetes." (PMID 37775767, 2023). "These patients were older, more often had diabetes and CKD, but less often had hypertension and hyperlipidemia, more often suffered cardiogenic shock and were more frequently mechanically ventilated, and had lower GFR, higher serum creatinine, and higher C-reactive protein on admission." (PMID 38068363, 2023). "Subphenotype 2 showed the highest median levels of NT-proBNP, hs-troponin T and CRP at baseline, the lowest percentage of patients with NYHA class I or II, the longest median duration of HF and these patients most often had a history of chronic renal failure or diabetes mellitus." (PMID 37327673, 2023). "Thus, stratifying the cohort by high vs. low CRP concentrations and computing the vitamin C dose–concentration relationship showed a comparable trend to the vitamin C requirements in people with diabetes relative to those without diabetes." (PMID 37891943, 2023). "Furthermore, we identified an inverse relationship between fish oil use and CHD incidence, which was significantly mediated by serum C-reactive protein (CRP) levels in individuals with prediabetes and by very-low-density lipoprotein cholesterol (VLDL-C) in patients with diabetes at baseline." (PMID 37513593, 2023). "Early cardiac complications were previously found to be more common in patients with severe strokes with medical history of HF, diabetes, higher creatinine levels, and ECG abnormalities; however, the association of CRP levels with early cardiac complications was not investigated." (PMID 37119383, 2023). "In addition, a significant negative correlation between CRP and Vit D levels existed in the diabetes group (r = 0.258)." (PMID 38136648, 2023). "Notably, CRP and ALT exhibited potential as indicators for renal disease, diabetes, and arthritis." (PMID 37626700, 2023). "Compared with other groups, participants in group 5 were more likely to be older; men; have hypertension, diabetes mellitus, and dyslipidemia; more likely to take antihypertensive, hypoglycemic, and hypolipidemic medications; and have a higher level of BMI, SBP, DBP, LDL-C, and Hs-CRP." (PMID 38093279, 2023). "Also, our study concluded that CRP and ALT might be used as indicators for renal diseases, diabetes, and arthritis diseases." (PMID 37626700, 2023). "DM: Diabetes mellitus; CRP: C-reactive protein; CVD: Cardiovascular disease; HTN: Hypertension; CKD: Chronic kidney disease." (PMID 37102036, 2023).
diabetes (continued). "These associations, particularly CRP during pregnancy, were independent of medical history confounders related to diabetes risk including GA, age, previous history of GDM, family history of diabetes as well as breastfeeding and weight or changes in weight." (PMID 37891561, 2023). "Through reviewing previous literatures and assessing the confounding, the final regression models were adjusted for age, PD duration, comorbidity of diabetes mellitus, serum albumin level, CRP level, fungal peritonitis, Gram-negative bacteria peritonitis, and multi-organism peritonitis." (PMID 37737145, 2023). "C-reactive protein levels in subgroup 1 were significantly higher when compared with the group without diabetes, with an average value of 73.47 mg/L, and 38.3 mg/L in subgroup 2, results which suggest a higher inflammation level in patients who had as comorbidity type two diabetes (p < 0.001)." (PMID 37627906, 2023). "Consequently, this study does not support the use of CRP as an objective marker for statin therapy in patients with diabetes." (PMID 37760885, 2023). "Similarly, there was a 1.15 mg/L increase in CRP for every 2.5 kg/m2 gain in BMI in the group with diabetes relative to an increase of 0.63 mg/L CRP for every 2.5 kg/m2 gain in BMI in the group without diabetes (p < 0.0001)." (PMID 37891943, 2023). "Furthermore, the group with diabetes had a significantly higher 1.21 mg/L increase in CRP for every 10 kg in weight gain relative to the group without diabetes (0.67 mg/L CRP per 10 kg weight gain; p = 0.0005)." (PMID 37891943, 2023). "A possible explanation for the mild reduction in CRP after CPAP therapy may be the existence of comorbidities such as obesity, arterial hypertension and diabetes in our included patients, whereas an RCT which only collected OSA free of any comorbidities reported a significant reduction in CRP." (PMID 35652886, 2022). "In the process of atherosclerosis, inflammation is one of the important pathological factors in which C-reactive protein (CRP), TNF-α, IL-6, and other inflammatory cytokines play an important role in the occurrence and development of large vessel atherosclerosis in diabetes." (PMID 36212957, 2022). "In addition, male sex, higher age, longer dialysis duration, diabetes, higher BUN, lower Cr, lower Alb, higher CRP and a greater number of comorbidities, including acute myocardial infarction (AMI), cerebral bleeding and cerebral infarction were associated with higher all-cause mortality." (PMID 35421178, 2022). "Comorbidities such as diabetes mellitus (DM), hypertension (HTN), and chronic kidney disease (CKD) as well as laboratory parameters such as lymphopenia, elevated inflammatory markers like c-reactive protein (CRP), and D-dimer are observed in severe disease and supposedly predict early mortality." (PMID 36060343, 2022). "However, few studies suggested that the magnitude of association between CRP and CVD mortality is comparable in people with and without diabetes." (PMID 36158788, 2022). "In addition, PISA showed a strong correlation with HbA1c, hs-CRP, and TNF-α, suggesting that PISA may be an effective index for evaluating periodontal disease and diabetic status in patients with diabetes and periodontal disease." (PMID 36140045, 2022). "In our subgroup analysis, it was found that whether adjustment for diabetes, hypertension, or CRP did not exert distinct effect on the pooled effect estimates." (PMID 36124237, 2022). "As a second step of validation, a multivariable model was applied and significantly longer LTLs could be demonstrated in the active treatment group also after adjusting for sex, age, smoking, hypertension, diabetes, IHD, CRP, NYHA class III and LTL at inclusion (p = 0.03)." (PMID 36014852, 2022).
diabetes (continued). "The therapy with this drug not only lowered the level of pro-inflammatory markers such as C-reactive protein (CRP) or TNF-α, but also increased levels of anti-inflammatory cytokines which ultimately led to reduce the inflammation in the blood serum of patients with diabetes." (PMID 35468904, 2022). "Besides sFRP5, parameters of glucose status: glucose and HOMA-IR, inflammatory markers: IL-6 and CRP showed significant differences between healthy controls and diabetes subjects, but not between subjects with and without DPP4i treatment." (PMID 36056109, 2022). "The serum high-sensitivity CRP (hs-CRP) levels can represent levels of CRP that are not detectable using usual methods and can assess even mild inflammation in many diseases, including cardiovascular disease and diabetes." (PMID 36330147, 2022). "A smooth curve with a saturation effect was found after adjusting for age, sex, race, income to poverty ratio, education level, marital status, smoking status, vigorous recreational activity, BMI, CRP, stroke, cancer, diabetes, CVD, energy, and uric acid (P for non-linearity = 0.004)." (PMID 36311643, 2022). "Additionally, from the reports obtained, we could extract the CRP and TNF-α in different races to investigate if there is an impact of demographic changes on CRP levels at the pre-diabetes stage." (PMID 36595749, 2022). "A systematic review and meta-analysis of hemodialysis death risk factors published in 2017 showed that all-cause and cardiovascular death are affected by multiple factors (age, gender, diabetes, CRP, CV, HbA1c, etc.), but did not explore the relationship between SUA and mortality." (PMID 35192651, 2022). "CRP is nonspecific inflammatory marker, a cytokine which may induce obesity, diabetes, neurological and cardiovascular events." (PMID 36217471, 2022). "Since in all the studies included with age adjusted, the prognostic significance of circulating testosterone might be independent of race, BMI, age, hypertension, diabetes, creatinine, CRP, and SHBG." (PMID 36124237, 2022). "Risk factors that are highly correlated with CVD in the Japanese population, such as BMI, hyperlipidemia, diabetes, smoking, gender, and high-sensitivity CRP, were not correlated with prevalence in this study, which conflicts with the conventional theory of cardiovascular disease." (PMID 34441936, 2021). "Diabetes, use of metformin, intake of often high quantities of non-nutritive sweeteners, inflammation (measured as CRP), and increased gastrointestinal permeability (measured as zonulin), which were variables included in this study, are known causes of faecal dysbiosis." (PMID 33806783, 2021). "Furthermore, we have shown that these new markers have a lower inter-individual variability; therefore, they can improve the predictive outcomes of CRP in patients with and without diabetes and in patients with and without dyslipidemia." (PMID 34947938, 2021). "Inflammatory biomarkers, including high-sensitivity CRP (median [IQR], 34.6 [6.68-81.73] vs. 18.0 [2.15-55.0] mg/L; p = 0.0045) and globulin (median [IQR], 27.9 [25.8-32.5] vs. 26.4 [23.7-29.7] g/L; p < 0.0001) were significantly higher in patients with diabetes." (PMID 34283900, 2021). "Following parameters emerged as significant independent predictors of persistent AF: EF < 60% (OR, 1.9), diabetes (OR, 2.1), COPD (OR, 1.8), previous cardiac surgery (OR, 3.1), valvular intervention (OR, 2.4), low hematocrit (OR, 1.9), low LDL (OR, 2.1), high HbA1c (OR, 2.0), and high CRP (OR, 2.7)." (PMID 33836659, 2021). "In addition, while analyzing 14-day mortality as the objective variable, some factors related to prognosis, such as BMI, CRP, comorbidities other than diabetes, and lactate levels were not examined." (PMID 34187294, 2021).
diabetes (continued). "In another study including persons with diabetes, persons with coronary heart disease but no diabetes, and control subjects, high CRP levels were related to low PON1 activity, suggesting that there is a mechanistic link between inflammation and the development of atherosclerosis." (PMID 34332593, 2021). "Associations between the classes and RHI were adjusted for age, gender, body mass index, diabetes, HDL-cholesterol, LDL-cholesterol, family history of ischaemic heart disease, smoking status, RA duration, DAS28 score, steroid dose, existing hypertension, and C-reactive protein." (PMID 34350216, 2021). "It is possible that the DASH diet may not be effective in reducing CRP levels in healthy adults, but rather in individuals with obesity and/or diabetes." (PMID 33816541, 2021). "Metabolic disorders include diabetes, overweight, or a combination of two out of five minor cardio-metabolic abnormalities (high waist circumference, low HDL, high triglycerides, impaired fasting glucose, high blood pressure, high C-reactive protein (CRP), insulin resistance)." (PMID 34501590, 2021). "Indeed, in patients without diabetes, elevated levels of CRP are related to future insulin resistance and development of type 2 diabetes." (PMID 34753497, 2021). "In the present study, we found that maternal first-trimester plasma taurine, measured at a mean gestation age of 9 weeks, was positively related to HOMA-β values in both multiparas and primiparas independent of age, BMI, CRP, family history of diabetes, history of PCOS, and physical activity." (PMID 33846497, 2021). "Laboratory parameters, including the serum urea nitrogen, high-sensitivity cardiac troponin I, myoglobin, D-dimer, lactate dehydrogenase, procalcitonin, C-reactive protein, and ferritin levels, were markedly higher in patients with diabetes than in those without diabetes." (PMID 33776910, 2021). "In our study, TNF-α level was associated with hyperglycemia, insulin resistance, and dyslipidemia, and MCP-1 level was associated with CRP level, but TNF-α and MCP-1 levels were not independent contributors to diabetes progression after adjustment for metabolic parameters." (PMID 31690939, 2020). "The D-dimer values and the CRP values in Stanford type B AAD patients were higher than those noted in healthy control subjects (P < 0.001), while there was significant difference in history of diabetes (P < 0.05), smoking (P < 0.01), and hypertension (P < 0.001)." (PMID 32509885, 2020). "According to some authors, C-reactive protein (CRP), as a protein of acute phase of inflammation, is a more informative marker of chronic systemic inflammation in the body since it supports the inflammatory series in patients with CP, obesity, and diabetes mellitus." (PMID 33456608, 2020). "However, other notable variables of appreciable accuracy were markers of diabetes control (FBS, RBS) inflammation (CRP), kidney function (potassium, BUN, creatinine and urinary albumin), haematological markers (haematocrit), and systolic blood pressure, among others." (PMID 33198349, 2020). "Also, higher CRP concentration was associated with higher odds of nephropathy and PAD in non-diabetes and higher odds of PAD in diabetes." (PMID 32665312, 2020). "We found that patients with diabetes and increased levels of TNFR1 showed a significantly higher 90-day mortality risk compared to the lower quartiles, however not when adjusting for CRP, although still significant in the highest quartile of TNFR1 vs the three lower quartiles." (PMID 32281000, 2020). "Moreover, vegetable intake was negatively associated with serum levels of C-reactive protein, IL-6, and TNF-α in healthy individuals without cardiovascular disease or diabetes mellitus." (PMID 33171846, 2020).